RUNX3 (RUNX family transcription factor 3)
Diseases named in the same sentence as RUNX3 in open-access papers (continued):
Sharing a sentence is not in itself a finding about the gene and the disease.
tumor (continued). "Since suppression of RUNX3 expression in 544 cells attenuated the xenograft tumor growth in recipient mice, we addressed whether RUNX3 in the exp‐CAFs contributes to co‐injected cancer cell proliferation and to neoangiogenesis in the tumors." (PMID 37641472, 2023). "RUNX3 is a well-known tumor suppressor and prognostic biomarker for patients with NSCLC." (PMID 37438719, 2023). "Since RUNX3 is a transcription factor, we speculated that a certain RUNX3‐regulated gene(s) is directly involved in the tumor‐promoting property of exp‐CAF 544 cells." (PMID 37641472, 2023). "Patients with increased/preserved SMAD4 and RUNX3 expression in either the tumor epithelium (HR = 0.34, 95% CI 0.18–0.66, p = 0.001) or the stromal compartment (HR = 0.34, 95% CI 0.2–0.57, p < 0.001) had significantly better prognoses compared to those with decreased/lost expression." (PMID 36900240, 2023). "Expression of RUNX3 in tumor nucleus and cytoplasm were both correlated with site." (PMID 36900240, 2023). "Whether re-activation of silenced RUNX3 using demethylating agents (e.g., azacytidine and decitabine) leads to terminal differentiation and tumor regression remain to be determined." (PMID 36766749, 2023). "Even if Runx3 in tumor cells contributes somehow to tumor progression, it might work through pathways other than the immune system." (PMID 37189103, 2023). "The effects of the re-expressed RUNX3 gene on tumour progression remain to be elucidated." (PMID 37759525, 2023). "According to current knowledge, RUNX2 acts as an oncogene and is related to the more aggressive forms of the disease, whereas RUNX3 exerts a tumour-suppressive role and could be used as a biomarker for early HCC detection." (PMID 37759525, 2023). "Conversely, tumor cells that showed high nuclear MYC expression stained poorly for RUNX3." (PMID 37400551, 2023). "The recurred tumor demonstrated spontaneous inactivation of the restored Runx3 allele without secondary oncogene activation." (PMID 37887282, 2023). "Analysis of our RNA‐seq data and published RUNX3 ChIP‐seq data suggested that RASL11A might play a role in the tumor‐promoting ability of the exp‐CAFs and that it is under the control of RUNX3 at the transcription level." (PMID 37641472, 2023). "Ten patient specimens with α‐SMA‐positive myofibroblasts in tumor stroma were analyzed for RUNX3." (PMID 37641472, 2023). "Moreover, we quantified the relative levels of circTENM3, RUNX3, and miR-558 in tumor tissue specimens using qPCR." (PMID 38007527, 2023). "While largely characterized as a tumor suppressor, RUNX3 can also be oncogenic in certain cancers." (PMID 36899853, 2023). "Moreover, evaluation of the microvessels with CD31 staining revealed significant reduction of microvessel numbers in the tumor sections with the RUNX3‐knockdown exp‐CAFs than those with the control cells." (PMID 37641472, 2023). "Regarding neoangiogenesis, microvessel detection with CD31 staining indicated that suppression of RUNX3 expression in the tumor‐promoting fibroblasts affected the microvessel numbers significantly and reduced the microvessel‐occupied areas with two out of three shRNAs." (PMID 37641472, 2023). "Therefore, we propose designating RUNX3 and similar acting proteins as “decision makers,” with their activities as tumor suppressors or oncogenes being dependent on the intactness of the decision-making machinery in cells." (PMID 36899846, 2023). "We propose that RUNX3 can mediate the tumor‐promoting ability of CAFs." (PMID 37641472, 2023). "It remains an interesting topic whether these different modifications occur sequentially or antagonistically to regulate the stability and tumor suppressor function of RUNX3." (PMID 36899853, 2023). "Although RUNX3 has long been considered a tumor suppressor in human cancers, several recent studies have shown that RUNX3 is upregulated during the development or progression of various malignant tumors, suggesting it may act as a “conditional” oncogene." (PMID 37190031, 2023).
tumor (continued). "In univariate analyses, high expression levels of IRS1 in stromal cytoplasm, RUNX3 in tumor (nucleus and cytoplasm) and stroma (nucleus and cytoplasm), and SMAD4 in tumor (nucleus and cytoplasm) and stromal cytoplasm were related to increased disease-specific survival (DSS)." (PMID 36900240, 2023). "This paradox results concerning RUNX3 might inevitably point to the debate that whether RUNX3 functions as a tumor suppressor gene or oncogene or even both were depending on specific tumor context." (PMID 35368900, 2022). "Thus, RUNX3 is fundamental for suppressing melanoma metastasis to secondary tissues, but the functional roles of RUNX proteins in tumor-associated NK cells require further investigation." (PMID 36231078, 2022). "Because of the small sample size, we could not draw meaningful conclusions regarding the relationship of RUNX3 expression with tumor stage." (PMID 36518886, 2022). "KRAS-activated cells could develop into ADCs when Runx3-mediated tumor suppress signaling pathways are abrogated." (PMID 36619616, 2022). "For two decades, our research group has been a pioneer in questioning as well as investigating whether the hypoxic tumor microenvironment regulates RUNX3." (PMID 36231060, 2022). "RUNX3 has been reported as a tumor suppressor in an increasing number of studies." (PMID 36429115, 2022). "We therefore believe that RUNX3 expression may be useful for predicting the recurrence or metastasis of this tumor, and it also has potential use as a novel target in future studies that examine drug therapies for CCRCC." (PMID 36518886, 2022). "In addition to its tumor suppressor function, RUNX3 can promote tumor development under special circumstances." (PMID 36429115, 2022). "It is shown that G9a may directly regulate RUNX3 to regulate the tumor suppressor function of RUNX3 by methylation." (PMID 36476345, 2022). "RUNX3 has been demonstrated to function as a tumor suppressor in many types of tumors." (PMID 36476345, 2022). "RUNX1 is a member of the RUNX family of transcription factors (RUNX1, RUNX2 and RUNX3), and is known to influence the malignancy of many neoplasms, including leukaemia, and to act as an oncogene or tumour suppressor gene with diverse functions depending on the tumour." (PMID 36085167, 2022). "Furthermore, it was mechanistically revealed that RUNX3 controls the expression of genes responsible for the tissue-residency of CD8+ TRM cells as Runx3 downregulation severely promoted tumor growth." (PMID 36231078, 2022). "RUNX3 as a tumor suppressor could directly interact with the β-catenin/TCF4 complex, blocking the binding of the complex to DNA and suppressing its transcriptional activity." (PMID 36429115, 2022). "Thus, in vivo overexpression of RUNX3 in CCRCC xenografts led to reduced tumor volume and weight and increased expression of E-cadherin." (PMID 36518886, 2022). "Therefore, RUNX3 methylation by G9a reduced RUNX3 transactivation activity and increased protein degradation by the cytosolic localization, which finally promoted tumor progression by the reduction of a tumor suppressor." (PMID 33116296, 2021). "In addition, their findings showed Runx3 overexpression promotes TILs tumor residency, which led to improved anti-tumor outcomes." (PMID 35087832, 2021). "Our results demonstrate the molecular mechanism of RUNX3 inactivation by G9a-mediated methylation for cell proliferation and antiapoptosis under hypoxia, which can be a therapeutic or preventive target to control tumor growth during early tumorigenesis." (PMID 33116296, 2021). "Primarily, RUNX3 was reported as a tumor-suppressor gene in multiple cancers." (PMID 34722267, 2021). "In addition, many functional studies have demonstrated that Runx3 is a tumor suppressor in many types of cancers but is a tumor promoter in other types." (PMID 33672337, 2021). "RUNX3 was frequently down-regulated in BC cell lines and primary tumours of Chinese women." (PMID 34884658, 2021).
tumor (continued). "Additionally, RUNX3 exerts both tumor suppressive and oncogenic functions in pancreatic cancer depending on mutational background and phenotypic readout." (PMID 33530588, 2021). "Repressed transactivation and impaired anti-tumor functions may be also due to RUNX3 mislocalization, which is frequently observed in gastric and breast cancer." (PMID 34421907, 2021). "Since the tumor vascularization in vivo is regulated by various factors affecting endothelial cells and our results may indicate RUNX3′s influence on angiogenic modulators, CM from A2780 and A13-2-12 cells was analyzed." (PMID 33530588, 2021). "The transcription factor RUNX3 has been described as a tumor suppressor." (PMID 33924679, 2021). "Recently, G9a was shown to interact with RUNX3, suggesting that G9a might directly modulate RUNX3 to control tumor suppressive functions of RUNX3." (PMID 33116296, 2021). "G9a-mediated methylation of RUNX3 under hypoxia promotes cancer cell proliferation by increasing cell cycle or cell division, while suppresses immune response and apoptosis, thereby promoting tumor growth during early tumorigenesis." (PMID 33116296, 2021). "Although p300, BRD2, and G9a interact with the same Runt domain of RUNX3, these data suggest that cells undergo differential lysine modifications of RUNX3 through interactions with these proteins to adequately adapt them to the varying tumor microenvironment." (PMID 33116296, 2021). "Further, although the B16-F10 mock control cells demonstrated a high potential of pulmonary metastasis, as expected, the metastatic potential was abolished by Runx3, whereas subcutaneous tumor formation was reduced by Runx3 to 61.5% compared to the mock control cells." (PMID 33672337, 2021). "This indicates that RUNX3 probably plays a pro-tumor role in AML." (PMID 34722267, 2021). "However, the mechanisms by which TrkB promotes these characteristics via BMP and RUNX3 and the signaling mechanisms that modulate the tumor-suppressive activities of BMP are unclear." (PMID 32731498, 2020). "Additionally, TrkB-mediated PI3K/AKT activation was shown to suppress the expression of Runx3 and Keap1 tumor suppressors that are commonly downregulated in malignant tumors." (PMID 32340410, 2020). "Additionally, overexpression of circREPS2 triggered an increase of circREPS2 and RUNX3 mRNA level while a reduction of miR-558 in excised tumor masses." (PMID 32721878, 2020). "RUNX3 was a well‐acknowledged tumour suppressor as a transcriptional factor." (PMID 32307917, 2020). "However, their aberrant expression in esophageal tissue biopsies also invite further investigation to be done to establish the role of RUNX3 in cancer is tumor suppressive or oncogenic." (PMID 32943993, 2020). "We found only one gene (RUNX3) hypermethylated in the colon primary tumours of our five patients." (PMID 32971738, 2020). "Therefore, although the de novo formation of oncogenic super-enhancers during cellular transformation promotes tumorigenesis, it is likely that RUNX3-mediated SE-driven the expression of RCAN1.4 plays an important role in tumor suppression in normal cells." (PMID 32771023, 2020). "Also, we found that in 06 cases with methylation as well as up-regulated EZH2 protein expression RUNX3 was downregulated in tumor tissue." (PMID 32943993, 2020). "And this may well explain the two‐edge role of RUNX3 in different tumours, because it seems like that RUNX3 functions as an oncogenic factors in some rare cases." (PMID 32307917, 2020). "RUNX3 is known to have tumor suppressive role in gastrointestinal cancers." (PMID 32943993, 2020). "Since several reports suggested low RUNX3 expression in GI cancers, our data, adds a new dimension to the biology of RUNX3 and suggests that RUNX3 to function in tumor suppressive manner and emphasizes the need to revisit our understanding of RUNX3 biology in GI cancers." (PMID 32943993, 2020).
tumor (continued). "We showed that Runx3 compensated Runx1 to contribute to neurofibromagenesis but that dual deletion of Runx1/3 in the Nf1fl/fl;DhhCre mice overcame the gene dose compensation and exhibited more durable effects on tumor initiation and/or maintenance." (PMID 31032403, 2019). "RUNX3 can be a tumor suppressor or an oncogene, depending on the cancer type." (PMID 31311113, 2019). "RUNX3 acts as a tumor suppressor in gastric cancer but functions as an oncogene in ovarian cancers." (PMID 31032403, 2019). "In this regard, it is worth emphasizing that in multiple types of tumours, RUNX3 is frequently inactivated by epigenetic alterations, which could in theory be reversed." (PMID 30535344, 2019). "To determine whether increased Runx3 expression in miR-301a−/− mice is responsible for recruiting T cells and reducing B16 tumor cell metastasis, we injected miR-301a−/− mice intravenously with shRNA-Runx3 lentivirus after implantation with B16 tumor cells." (PMID 31122259, 2019). "In addition, RUNX3 was deemed to be a nuclear regulator in IL-dependent NK cell activation and thereby participated in tumor immune escape mechanism." (PMID 29636640, 2018). "Runt-related transcription factor 3 (RUNX3) is known to function as a tumor suppressor." (PMID 29796116, 2018). "RUNX3 is known to be a tumor suppressor exhibiting anti-tumor activity in several cancers." (PMID 29651226, 2018). "RUNX3 can function as either a tumor suppressor or oncogene, depending on tumor type." (PMID 29966370, 2018). "Additionally, the number of tumor-infiltrating immune cells influences the measured tissue-based RUNX3 gene expression because of an inherent RUNX3 expression in immune cells." (PMID 29342962, 2018). "The tumor suppressors p21 and RUNX3 were affected by PIM1 kinase knockdown, which may provide a partial explanation for the pleiotropic effects of this multifunctional kinase." (PMID 29467592, 2018). "RUNX3 is localized on chromosome 1p.13-p36.11, where loss of heterozygosity (LOH) is frequently observed in multiple cancers, demonstrating its potential role as a tumor suppressor." (PMID 29254144, 2017). "Runt-related transcription factor 3 (RUNX3) is a tumor suppressor in many human solid tumors." (PMID 29254144, 2017). "To further validate our hypothesis, we transfected CD8+ T cells with control-/RUNX3-siRNA before co-culturing in tumor milieu and then did ChIP assay after 72 h of co-culture." (PMID 28487507, 2017). "Studies in human cell lines further investigated the physiologic targets of miR106a, and showed that miR106a could target tumor-suppressor genes, such as RUNX3, Twist1, pRB and E2F1." (PMID 27926519, 2017). "This information indicated a pivotal role of RUNX3 in FOXP3 regulation in tumor-CD8+ Treg cells." (PMID 28487507, 2017). "As tumor cell migration and invasion are essential for metastasis, our findings hinted that RUNX3 may have the potential to regulate RCC metastasis." (PMID 29254144, 2017). "RUNX3 was downregulated in RCC tumor tissue specimens as compared with normal renal tissues." (PMID 29254144, 2017). "Non-lymphocytic infiltrated tumors may require additional interventions aimed at promoting optimal inflammation and innate immune activation in the tumor microenvironment, perhaps by increasing RUNX3-mediated inflammatory signaling." (PMID 27566570, 2016). "In addition, we found that subgroup meta-analysis by geographical populations showed p16, RUNX3 and PRDM2 hypermethylation was a common risk factor between HCC tumor tissues and normal tissues in HCC patients." (PMID 27835605, 2016). "For example, we identified a region of 24 contiguous probes hypermethylated in scalp-derived fibroblasts within the gene RUNX3 –a tumor suppressor that plays an integral role in regulating cell proliferation and the rate of apoptosis (see S2 Fig and S2 Table for all significant DMRs)." (PMID 26913521, 2016). "RUNX1 and RUNX3 were originally considered as tumor suppressors." (PMID 27007162, 2016).